SOX2 (SRY-box transcription factor 2)
Diseases named in the same sentence as SOX2 in open-access papers (continued):
Sharing a sentence is not in itself a finding about the gene and the disease.
gastric cancer (continued). "Based on our data, the percentage of cardiac cancers may influence the result of predictive value of Sox2 in total gastric cancer." (PMID 28046028, 2017). "Therefore, we evaluated the expression of ALDH1A1 and Sox2 in gastric cancer samples, and, with respect to stratification, analyzed their correlation with pathological parameters and patient survival." (PMID 28046028, 2017). "Interestingly, in the case of gastric cancer, reports regarding the levels of SOX2 expression during tumor progression are conflicting." (PMID 28388544, 2017). "The role of Sox2, however, was shown to be paradoxical in gastric cancer." (PMID 28046028, 2017). "In addition, Sox2 has been shown to inhibit migration and invasion by upregulating p21 expression in gastric cancer." (PMID 28046028, 2017). "More than one miR has also been reported to target SOX2 in gastric carcinoma." (PMID 28388544, 2017). "This study reveals that SOX2, regularly expressed in the basal cell layer of normal prostatic glands, is substantially downregulated, most likely by gene promoter methylation, in PC epithelia and cell lines, as previously observed in gastric cancer." (PMID 26540632, 2016). "Our data also showed that there was a positive correlation between IL-17RB and Oct4, Nanog, Lgr5, or Sall4 mRNA expression, and that the expression of Oct4, Sox2, and Sall4 proteins increased in proportion to the increased expression of IL-17RB in gastric cancer tissues." (PMID 27146881, 2016). "In renal cell carcinoma and gastric cancer, the expression of SOX2 has been found to be reduced." (PMID 26370982, 2015). "Supporting this hypothesis, a survey performed on the Oncomine database showed that SOX2 ranked among the top 10% genes with copy number gains in gastric cancer." (PMID 25300947, 2014). "Moreover, we show that SOX2 locus copy number gain is a frequent event in gastric cancer, explaining SOX2 protein expression and also pinpointing a genomic region frequently subjected to genomic instability." (PMID 25300947, 2014). "SOX2 could also act as a tumor suppressor gene, being frequently downregulated in gastric cancers, some of which appeared due to epigenetic silencing through DNA methylation." (PMID 25340937, 2014). "However, Sox2 is frequently down-regulated in gastric cancers and inhibits cell growth through cell cycle arrest and apoptosis." (PMID 23451179, 2013). "Importantly, siRNA-mediated silencing of Sox2 gene in SC remarkably suppressed tumor growth in nude mice gastric cancer xenograft." (PMID 23554769, 2012). "Furthermore, most of them also exhibited changes in their expression after SOX2-overexpression, at least in two gastric cancer cell lines." (PMID 21304604, 2011). "Furthermore, exogenous miR-126 over-expression as well as siRNA-mediated knockdown of SOX2 significantly enhanced the anchorage-dependent and -independent growth of gastric cancer cell lines." (PMID 21304604, 2011). "Expression of SOX2 and miR-126 in gastric cancer cell lines." (PMID 21304604, 2011). "Although it is controversial as to whether miR-126 is a tumor suppressive or oncogenic miRNA, at least in the present study, we demonstrated that miR-126 acts as an oncogene by targeting SOX2 in gastric cancer cells." (PMID 21304604, 2011). "In addition, miR-126 was highly expressed in some cultured and primary gastric cancer cells with low SOX2 protein levels." (PMID 21304604, 2011). "We further revealed that SOX2 plays important roles in growth inhibition through cell cycle arrest and apoptosis, indicating that SOX2 may have tumor-suppressive functions in gastric cancer cells." (PMID 21304604, 2011). "In order to find novel miRNAs that regulate SOX2 expression in gastric cancer, we performed computational analysis using a miRNA target database, MicroCosm Targets (formerly miRBase Targets), and tried to identify miRNAs that target the SOX2 3′-UTR according to the following criteria." (PMID 21304604, 2011).
gastric cancer (continued). "To validate the results of computational analysis, we examined whether or not miR-126 and miR-522 can repress the expression level of the endogenous SOX2 protein in SOX2-expression-positive gastric cancer cell lines." (PMID 21304604, 2011). "Among the miR-126-up-regulated cases, three (FG6, FG21 and FG24) exhibited lower levels of SOX2 protein than paired non-cancerous mucosae, suggesting that high levels of miR-126 expression contribute to low levels of SOX2 protein at least in some primary gastric cancers." (PMID 21304604, 2011). "Downregulation of SOX2 could be detected in precursor lesions of gastric cancer such as intestinal metaplasia and Helicobacter pylori infection, a strong risk factor of gastric cancer, could induce intestinal metaplasia through inhibition of SOX2 expression." (PMID 20814443, 2010). "Finally, we investigated the methylation status of SOX2 in human gastric cancer cell lines and primary gastric carcinoma tissues." (PMID 18268498, 2008). "However, among the 52 patients with advanced gastric cancers, Kaplan–Meier analysis demonstrated that those with cancers showing SOX2 methylation had a significantly shorter survival than those without this methylation (P=0.0062)." (PMID 18268498, 2008). "We have demonstrated, for the first time, SOX2 as a tumour-suppressive gene in gastric cancers, and our findings may lead to new therapeutic approaches for gastric cancer." (PMID 18268498, 2008). "Moreover, knockdown of SOX2 by siRNA upregulated phosphorylated Rb and downregulated p27Kip1 in the two gastric cancer cell lines." (PMID 18268498, 2008). "Furthermore, our previous study demonstrated that SOX2 protein levels were reduced in gastric carcinoma tissues compared with normal gastric epithelia." (PMID 18268498, 2008). "Despite these reverse regulations of CDX2 and SOX2, a study of gastric carcinoma has not found a reverse association of the two factors when examined by IHC staining, suggesting retained expression of both factors due to deregulation of the networks that physiologically determine tissue identities." (PMID 40149431, 2025). "Therefore, the oncogenic functions of Sox2 are controversially discussed in gastric cancers, in which Sox2 might also have tumor-suppressor functions." (PMID 32849491, 2020). "Matsuoka 30 analyzed the expression levels of OCT4 and SOX2 in gastric cancer specimens by immunohistochemistry, and found that positive expressions of SOX2 and OCT4 in gastric cancer tissues were associated with gastric cancer invasion, may be independent factors affecting the prognosis." (PMID 32788883, 2020). "Notably, SOX2 expression also appears to vary with different mucosal subgroups in gastric cancer." (PMID 28388544, 2017). "However, others demonstrated that Sox2 operates as an oncogene in gastric cancer." (PMID 28046028, 2017). "The expression of stemness factors including Oct4, Sox2, Nanog and Lin28, which are known to be sufficient to reprogram somatic cells to pluripotent stem cells, were found to be significantly increased in fused cells compared to the parental gastric cancer cells by western blot and real-time RT-PCR." (PMID 26498753, 2015). "Besides gastric cancer, Pre-miR-126 over-expression reduced the SOX2 protein level in mouse ES cells, suggesting that miR-126 may generally control SOX2 expression, at least in two species (human and mouse) and various cell lineages, including ES cells." (PMID 21304604, 2011). "These expression differences and/or transcriptional cofactors might also be critical for control of expression of the downstream target genes of SOX2 in gastric cancer cells, and further studies are necessary to clarify the roles of SOX2 in the regulation of its target genes." (PMID 21304604, 2011). "Here, we assessed whether microRNAs (miRNAs) regulate SOX2 expression in gastric cancers." (PMID 21304604, 2011).
gastric cancer (continued). "Moreover, SOX2 downregulation has been found to be frequent in clinical samples, cancer cell lines and primary cultures of human cancers such as choriocarcinomas and gastric cancer." (PMID 20814443, 2010). "The role of stem cell transcription factors SOX2 and CDX2 is of particular interest in the pathogenesis of gastric cancer." (PMID 40149431, 2025). "Downregulation of JMJD3 resulted in a significant decrease in the levels of CD44, SOX2, OCT4, and LIN28 in gastric cancer cells." (PMID 41184226, 2025). "These additional signals may also play a role in gastric carcinomas, given that WNT/APC/β-catenin pathway-activated mutations are not universally observed in CDX2-induced gastric cancers and are observed in lower frequency in the sub-set with SOX2-expression maintenance." (PMID 40149431, 2025). "Specifically, gastric cancer cells with enhanced BATF2 expression exhibited significantly lower levels of the cancer stem cell markers CD44, NANOG, and SOX2 than the control cells." (PMID 39629124, 2024). "This study expands on BATF2's role in gastric cancer, demonstrating how it interacts with PTEN to suppress the AKT/β-catenin/ABCG2 signaling pathway, impacting stem cell markers like ABCG2, CD44, SOX2, and NANOG, based on in vivo and in vitro analyses." (PMID 39629124, 2024). "A study with gastric cancer samples and cell lines revealed that linc-ROR led to the upregulation of several key stemness transcriptional factors such as OCT4, SOX2, Nanog, and CD133, promoting proliferation and invasion of gastric cancer stem cells." (PMID 36827545, 2023). "The result showed that a significant correlation was found between KMT2A and the stemness-related gene sets, including tumor stemness-related signature (CD44/CD133/Sox2/OCT4) and gastric cancer-specific stemness signature (Sox/FOXM1)." (PMID 38025523, 2023). "As a ceRNA, NONHSAT160169.1 decoys hsa-let-7c-3p and increases the level of SOX2, thereby aggravating lapatinib resistance in HGC-27 gastric cancer cells." (PMID 38012281, 2023). "The MKN45 cells with GRP78 knockdown exhibited decreased formation of colonies and spheroids and decreased expression of gastric cancer stem cell–like markers (LGR5, CD24, CD44, and ALDH1) and stemness-related transcriptional factors (SOX2 and Nanog)." (PMID 35740372, 2022). "The expression of OCT4, SOX2, Nanog, and KLF4 was examined in six gastric cancer cell lines at the basal level and upon a spheroid culture." (PMID 36661504, 2022). "EVs-L-PGDS inhibited gastric cancer growth, induced cell apoptosis, reduced the expression of stem cell markers including Oct4, Nanog, and Sox2, and inhibited STAT3 phosphorylation in SGC-7901 gastric cancer cells." (PMID 35741334, 2022). "Ectopic AKAP8L in gastric cancer cells and spheroids elevated the expression of stem cell markers, including Lgr5, CD133, CD44, Oct4, Sox2, as determined by qPCR, Western blot analysis." (PMID 36522343, 2022). "Overall, pluripotency factor expression was divergent in the gastric cancer cell lines as shown in the prominent expression of KLF4 and Nanog in SNU-601 and of SOX2 in SNU-484." (PMID 36661504, 2022). "Expression of four pluripotency factors (OCT4, Nanog, SOX2, and KLF4) at the transcript level in gastric cancer tissue was analyzed against various pathological parameters using RNASeq data downloaded from the TCGA database." (PMID 36661504, 2022). "This study aimed to define the role of pluripotency factors (OCT4, SOX2, Nanog, and KLF4) in gastric cancer progression, spheroid forming capacity, and drug resistance." (PMID 36661504, 2022). "Mechanistically, EVs-L-PGDS reduced the expression of stem cell markers including Oct4, Nanog, and Sox2 and inhibited STAT3 phosphorylation in gastric cancer cell SGC-7901." (PMID 35087591, 2022).
gastric cancer (continued). "The study showed that miR21 expression of gastric cancer cells increases when cells are treated with DCA, leading to SOX2 expression suppression and the simultaneous induction of CDX2 expression under BA treatment." (PMID 34638550, 2021). "Gastric cancer cells resistant to this drug displayed increased CMIP expression, the latter correlated with tumor size and lymph node metastasis by a SOX2-mediated mechanism." (PMID 33917766, 2021). "Further studies have shown that BCAR4 activates the Wnt/β-catenin signaling pathway and up-regulates the expression of stemness markers nanog, OCT3/4, SOX2, c-Myc, and KLF4, which further enhance gastric cancer cell stemness and DDP resistance." (PMID 32460771, 2020). "It is apparent that stem cell markers Oct3/4, Sox2 and CD44 maintain the stemness of gastric cancer in tumorsphere cells." (PMID 32160650, 2020). "Very fascinatingly, we found that upregulation of HOXA11 in gastric cancer cells resulted in increased expression of cancer stem cell factors such as CD44, CD90, CD133 and Bmi1 as well as pluripotency markers Nanog and Sox2 and vice versa." (PMID 31695791, 2019). "It has been noted that SOX2 is a tumor suppressor that inhibits cell proliferation and metastasis by regulating PTEN in gastric cancer." (PMID 30733645, 2019). "The expression of SOX2 (P < 0.05, P < 0.05) and OCT4 (P < 0.05, P < 0.05) in gastric cancer cells treated with 50 μg exosomes were significantly decreased compared to the control group." (PMID 30031392, 2018). "Among these genes, deregulation of STAT3, GATA6, SOX2, and FOXA2 in gastric cancer was already reported previously in independent studies." (PMID 29720137, 2018). "Our analysis, thus, showed that abnormal expression of BMP1, COL1A1, STAT3, GATA6, SOX2 and FOXA2 forms an ubiquitous molecular signature of gastric cancer patients in Southwestern Taiwan." (PMID 29720137, 2018). "In gastric cancer, stem cell related factors ALDH1 and Sox2 were used as markers to identify the gastric CSCs." (PMID 28046028, 2017). "Elevated mRNA levels of OCT4, NANOG, SOX2, LIN28, and CD133 have also been identified in tumorigenic hybrid cells derived from mesenchymal stem cells and gastric cancer cells." (PMID 28768501, 2017). "We analyzed how the expression levels of Sox2 and ALDH1A1 individually correlate with overall survival in a total 116 gastric cancer patients with follow-up data." (PMID 28046028, 2017). "The results of western blot showed that the expression of CD44, SALL4, c-MYC, Oct4, Nanog, and Sox2 proteins also increased in 1 μM and 10 μM DIM-treated gastric cancer cells." (PMID 26918831, 2016). "This subgroup, showing SOX2 expression but a down-regulated expression of CDX2, has previously been shown to predict a worse patient outcome in gastric cancer." (PMID 27411517, 2016). "We also detected the expression of stem cell markers including Oct-4, Sox-2, Glil, CD44, and CD133 in the primary sites of gastric cancer and analyzed the correlation between these stem cell markers and Bmi-1 by spearman rank correlation test." (PMID 27644439, 2016). "Here, we used a retrospective, observational study to assess the expression and prognostic value of the transcription factors SOX2 and CDX2 in gastric cancer." (PMID 25300947, 2014). "As tumors that are more differentiated generally behave in a less aggressive fashion, we questioned the relevance of two differentiation markers, SOX2 and CDX2, for the biological behavior of gastric cancers." (PMID 25300947, 2014). "Our aim was to analyze the clinical relevance of SOX2 and CDX2 expression in gastric cancer biology." (PMID 25300947, 2014). "We found that miRNA-126 (miR-126) repressed SOX2 expression by targeting its 3′-UTR, and then performed functional analyses of miR-126 in gastric cancer cells." (PMID 21304604, 2011). "Additionally, metformin activates the cGAS‐STING signaling pathway by inhibiting SOX2/AKT, offering potential for enhancing gastric cancer immunotherapy." (PMID 39834553, 2025).
gastric cancer (continued). "Moreover, ginsenoside Rg3 can upregulate miR‐429 to inhibit SOX2 and the PI3K/Akt/mTOR signaling axis, thereby reducing cisplatin resistance in gastric cancer cells." (PMID 39834553, 2025). "On the other hand, gastric cancers with CDX2 induction and SOX2-retained expression could benefit from future approaches targeting chromosome instability as a process." (PMID 40149431, 2025). "In contrast, SOX2 (SRY-related HMG Box 2), a stem cell factor that specifies the normal foregut and is expressed in normal gastric epithelium, is down-regulated in sub-sets of gastric cancers." (PMID 40149431, 2025). "Hence, our study has unveiled the NONHSAT160169.1/hsa-let-7c-3p/SOX2 signaling pathway as a novel and pivotal axis for comprehending and surmounting lapatinib resistance in the treatment of HER2-positive gastric cancer." (PMID 38012281, 2023). "Gastric cancer stemness can be determined by investigating the expression of cell surface markers, namely CD24, CD44, and LGR5, and stemness-related transcriptional factors, namely Nanog and SOX2." (PMID 35740372, 2022). "As expected, both tumorsphere formation assay, CD44 expression detected by flow cytometry and stemness related markers (SOX-2, OCT-4, Nanog) detected by WB confirmed that miR-144-3p could attenuate the stemness of gastric cancer cells." (PMID 34657624, 2021). "In addition, RA decreased the expression of CSC markers (CD44 and ALDH) and stemness genes (KLF4 and SOX2) and inhibited CSC properties such as tumorspheres formation in gastric cancer." (PMID 34400945, 2021). "Another important point to be considered is that not all Sox2 expresser cells may be actually able to use Sox2 to run Sox2-dependent transcription, as studies with traceable Sox2 reporter plasmids on MCF-7 and gastric cancer cells have shown." (PMID 33228022, 2020). "Nishii 28 found that high expression of stem cell markers could isolate gastric cancer cell line with high potential for peritoneal metastasis, such as CD44, OCT4 and SOX2." (PMID 32788883, 2020). "The data showed that HMGCS1 could localize into nuclei, upregulate Oct4 and SOX-2 levels, and bind to Oct4 and SOX-2 promoters in gastric cancer cells." (PMID 32349352, 2020). "In IM, a precancerous lesion of gastric cancer, most studies showed that SOX2 expression was absent." (PMID 30733645, 2019). "The predictive value of Sox2 expression in patients with cardiac or non-cardiac gastric cancer was analyzed." (PMID 28046028, 2017). "Although stemness-related factors ALDH1A1 and Sox2 have been used as markers to identify gastric CSCs, the expression pattern and significance of these factors in gastric cancer have not been sufficiently demonstrated." (PMID 28046028, 2017). "To clarify the role of Bmi-1 in stemness of gastric cancer, we checked the expression of Bmi-1 in microsphere and found that sphere cells from SGC7901 and MKN45 cell lines overexpressed Bmi-1 and other stem cell markers Oct-4, Sox2, Nanog, CD44, and CD133." (PMID 27644439, 2016). "RASSF1A, p14ARF, and MGMT; CHRNA3, DOK1, and GNMT; p16, hMLH1, MINT1, MINT2, MINT12, MINT25, and MINT31; APC, CDH1, MHL1, CDKN2A, CDKN2B, and RUNX3; CDH1; DKK3; PTEN; MGMT; TFPI2; CACNA2D3; PCDH10; SOX2; MAL; and COX2 were previously reported to be hypermethylated in gastric cancer." (PMID 26121593, 2015). "In this study, miR-126 expression was found to be relatively high in SOX2-expression-negative gastric cancer cell lines, and was aberrantly up-regulated in some primary gastric cancer cases compared with the paired non-cancerous mucosae." (PMID 21304604, 2011). "Taken together, our results indicate that miR-126 is a novel miRNA that targets SOX2, and PLAC1 may be a novel downstream target gene of SOX2 in gastric cancer cells." (PMID 21304604, 2011).